LZTS1-AS1 (LZTS1 antisense RNA 1)
Gene: Long non-coding RNA gene on chromosome 8 (20,275,773 to 20,290,458, forward strand). Ensembl gene ENSG00000253733.
Gene Ontology:
Molecular function: structural constituent of ribosome
Cellular component: ribosome
Diseases named in the same sentence as LZTS1-AS1 in open-access papers:
LZTS1-AS1 is named in the same sentence as 3 diseases in open-access papers, as found by Europe PMC text mining. Sharing a sentence is not in itself a finding about the gene and the disease. The quoted sentences say what the papers report.
rheumatoid arthritis (1 paper, 2023). A chronic, systemic autoimmune disorder characterized by inflammation in the synovial membranes and articular surfaces. "Leucine zipper tumor suppressor 1 (LZTS1) antisense RNA 1 (LZTS1-AS1) is a lncRNA located at Chr8p21.3, which has been reported to be associated with rheumatoid arthritis." (PMID 37403096, 2023).
LZTS1-AS1 also shares sentences with these, for which no sentence is quoted: autoimmune disease (1 paper); celiac disease (1).